ZBTB21 (zinc finger and BTB domain containing 21)
Description:
Acts as a transcription repressor.
Synonyms: KIAA1227; ZNF295
Tractability: PROTAC: UniProt records ubiquitination sites on it; ubiquitination databases record sites on it; its protein half-life has been measured.
Target class: Transcription factor
Gene: Protein-coding gene on chromosome 21 (41,986,831 to 42,010,387, reverse strand). Ensembl gene ENSG00000173276.
Subcellular location: Nucleus
Subcellular location (Human Protein Atlas): Nucleoplasm
Gene Ontology:
Molecular function: DNA-binding transcription repressor activity, RNA polymerase II-specific; methyl-CpG binding; POZ domain binding; protein binding; DNA-binding transcription factor activity, RNA polymerase II-specific
Biological process: negative regulation of transcription by RNA polymerase II; negative regulation of DNA-templated transcription; regulation of transcription by RNA polymerase II
Cellular component: nucleoplasm; nucleus
Genetic constraint (gnomAD): Loss-of-function variants: 12 observed, 40.84 expected, observed/expected ratio (o/e) 0.29, 90% interval 0.19 to 0.48. The upper end of that interval is the gene's LOEUF score, 0.48, which puts it in group 2 of 6, group 1 being the genes least tolerant of losing a copy. Missense variants: 1,050 observed, 1,152.9 expected, observed/expected ratio (o/e) 0.91, 90% interval 0.87 to 0.96. Synonymous variants: 458 observed, 443.34 expected, observed/expected ratio (o/e) 1.03, 90% interval 0.96 to 1.12.
Homologues: Orthologues: macaque ZBTB21 (99% identical), mouse Zbtb21 (86% identical), dog ZBTB21 (86% identical), rat Zbtb21 (86% identical), chimpanzee ZBTB21 (81% identical), rabbit ZBTB21 (66% identical), guinea pig ZBTB21 (61% identical), tropical clawed frog zbtb21 (60% identical), pig ZBTB21 (59% identical), zebrafish zbtb21 (9% identical). Paralogues in human: ZBTB33 (13% identical), BCL6 (12% identical), NACC2 (11% identical), ZBTB46 (10% identical), ZBTB49 (10% identical), BCL6B (10% identical), ZBTB14 (10% identical), NACC1 (9% identical), ZNF280D (9% identical), ZBTB7B (8% identical), ZNF280C (8% identical), PRDM13 (8% identical), and 16 more.
Diseases named in the same sentence as ZBTB21 in open-access papers:
ZBTB21 is named in the same sentence as 11 diseases in open-access papers, as found by Europe PMC text mining. Sharing a sentence is not in itself a finding about the gene and the disease. The quoted sentences say what the papers report.
Cerebellar hypoplasia (1 paper, 2023). Cerebellar hypoplasia is a descriptive term implying a cerebellum with a reduced volume, but a normal shape and is stable over time. "Comparing these four models suggests that at least one gene in the region that is trisomic in both Ts1Cje and Ts65Dn mice but is not trisomic in Ts1Rhr mice (Sod1 to Setd4 and Ripk4 to Zbtb21) contributes to cerebellar hypoplasia." (PMID 36995257, 2023).
hearts defects (1 paper, 2024). "However, a study of DS individuals found that congenital hearts defects were associated with two short copy number variants located between RIPK4 and PRDM15 and within ZBTB21 respectively, implicating this region in DS-CHD." (PMID 38266108, 2024).
Hypertension (1 paper, 2024). The presence of chronic increased pressure in the systemic arterial system. "ZBTB21 has been linked to hypertension in the Uyghur people." (PMID 38612670, 2024).
cancer (2 papers, 2021). A tumor composed of atypical neoplastic, often pleomorphic cells that invade other tissues. "A few candidate genes, such as ZBTB21, MTSS2, and EBF4, still have elusive functional mechanisms, while belonging to families of genes with suggested roles in cancer susceptibility." (PMID 34067022, 2021).
tumor (1 paper, 2026). "Genetic ablation of ZBTB21 unleashes pyroptotic cell death and enhances tumor antigen presentation, establishing a self-reinforcing cycle that recruits and activates CD8+ T cells." (PMID 41655210, 2026).
ZBTB21 also shares sentences with these, for which no sentence is quoted: Down syndrome (2 papers); Fanconi anemia (1); Intellectual disability (1); metabolic disorders (1); neurological diseases (1); theileriasis (1).